PER2 (period circadian regulator 2)
Diseases named in the same sentence as PER2 in open-access papers (continued):
Sharing a sentence is not in itself a finding about the gene and the disease.
Anxiety (19 papers, 2012 to 2025). Intense feelings of nervousness, tension, or panic often arise in response to interpersonal stresses. "Deletion of Per2 in mouse astrocytes reduced despair and anxiety associated with increased GABA transporter 2 and dopamine receptor D3 mRNA and reduced glutamate levels in the NAc." (PMID 37441675, 2023). "Genetic and adeno-associated virus-mediated deletion of Per2 in glial cells of mice leads to reduced despair and anxiety." (PMID 34112905, 2021). "Inhibition of Per1/Per2 expression in the nucleus accumbens (NAc) of wild-type mice also produces anxiety-like behavior, suggesting a causal role for these core clock components in the NAc for regulating anxiety." (PMID 32066704, 2020). "We tested this hypothesis by assessing behaviors associated with anxiety, depression, and motor function, as well as molecular and physiological properties of MSNs in mice with a selective knockout of Bmal1 and Per2 from striatal MSNs." (PMID 35755440, 2022). "Chronic social defeat stress induced mPer1 and mPer2 expression in the NAc and elective Per1 and Per2 knockdown in the NAc increased anxiety-like behavior as seen in the mPer1/mPer2 mutant animals." (PMID 37441675, 2023). "All other variants (PER2, PER3 VNTR, PER3A, CLOCK3111, CRY1, and CRY2 SNPs) were directly associated with anxiety symptoms following bootstrap analysis." (PMID 35365695, 2022). "Two of the rules with the highest lift values show the combination of CLOCK3111-TC, CRY2-AG, and PER2-AG as a significant predictor of anxiety." (PMID 35365695, 2022). "The conditional ablation of Bmal1 or Per2 from striatal MSNs affected anxiety-related behaviors differently." (PMID 35755440, 2022). "Concomitant knockdown of per1 and per2 in the nucleus accumbens of mice also elevates anxiety-like behavior." (PMID 34842772, 2021). "ClockΔ19 mice show decreased anxiety-like behavior, whereas loss of functional PER1 and PER2 has the opposite effect." (PMID 29230328, 2017). "This suggests that circadian fluctuations of corticosterone exert strong influence on CeA and other parts of the fear and anxiety circuitry, but spare regulation of Per2 and its targets in the BLA." (PMID 24376834, 2013). "A similar result was found in global Per2 knockout mice assessed in the open field, whereas assessment of genome-wide deletions of either Per1 or Per2 in the elevated plus-maze revealed mixed outcomes on anxiety-like behavior." (PMID 35755440, 2022). "Because anxiety-like behaviors are mildly affected by the conditional Bmal1 and Per2 knockout in our study, it is tempting to speculate about a contributing or compensatory role of striatal astrocytes with functional circadian clocks on behavioral control." (PMID 35755440, 2022). "In contrast, others have reported increased anxiety-like behaviors in Per2 knockdown mice." (PMID 33509094, 2021). "Further supporting a role for Per genes outside of the SCN in the modulation of mood and anxiety-like behaviors, Spencer and colleagues showed that knocking down both Per1 and Per2 in the nucleus accumbens was sufficient to increase anxiety-like behavior in mice." (PMID 29230328, 2017). "Clock-mutant mice showed reduced anxiety, whereas animals with decreased PER1 and PER2 expression were more likely to exhibit fearful behavior." (PMID 39408776, 2024). "Because Per1 and Per2 negatively regulate NPAS2/BMAL1 transcription, this further supports a role for NPAS2 in the regulation of anxiety-like behaviors." (PMID 29163035, 2017). "A different Per2 mutant mouse (Per2ldc), which also has a deletion that incorporates the PAS domain, was found to have inconsistent anxiety-like behaviors across measures in the elevated plus maze and light/dark box." (PMID 29230328, 2017). "However, loss of functional Per2 does not result in consistent effects on anxiety-like behavior." (PMID 29230328, 2017).
Anxiety (continued). "In another study involving animals, mice lacking PER1 and PER2 expression exhibited increased anxiety compared to wild-type controls." (PMID 39408776, 2024). "For males, the most frequently occurring variants were PER2-GG, PER3B-GG, CRY2-GG, and CLOCK3111-TC, with age, but not MEQ, significantly predicting the risk of anxiety." (PMID 35365695, 2022). "Despite findings suggesting increased anxiety-related behavior in the open field and elevated plus-maze in C57 female mice, sex-specific effects were prominent in the OFT in Per2 cKO only." (PMID 35755440, 2022). "In contrast, we did not observe an effect on the time spent in the open section of the O-maze when AAV9 Gfap-iCre was injected into the NAc, suggesting that glial Per2 in the NAc was not involved in the regulation of anxiety-related behavior." (PMID 34112905, 2021). "Both models lacking Per2 in Gfap-expressing cells (termed GPer2 and vGPer2) were assessed for despair- and anxiety-related behavior using the FST and O-maze test, respectively." (PMID 34112905, 2021). "In contrast, mice lacking both Per1 and Per2 display elevated anxiety-like behavior, whereas mice lack either Per1 or Per2 do not have altered anxiety-like responses." (PMID 32066704, 2020). "Besides, they spent more time in the open field (an anxiety-provoking space) of the elevated O-maze, indicating a reduced anxiety-like behavior in mice lacking Per2 in glial cells." (PMID 35845604, 2022). "To test whether the observed reduced despair and anxiety are specific to glial Per2 function, we produced mice lacking Per2 in neurons by utilizing the PHP.eB vector for genetic manipulation in adult animals." (PMID 34112905, 2021). "Exclusive deletion of Per2 in glia of the NAc reduced despair, but had no influence on anxiety." (PMID 34112905, 2021). "From this we conclude that Per2 in glia of the NAc may not be important for anxiety-related behavior and specifically affects despair." (PMID 34112905, 2021). "However, neuronal Per2 knockout also reduces despair, but not anxiety responses." (PMID 37441675, 2023). "Interestingly, neuronal Per2 knock-out also reduces despair, but does not influence anxiety." (PMID 34112905, 2021). "Reduced Per2 expression led to decreased immobility in both the TST and FST performed during the test phase, without significantly affecting locomotion or anxiety-like behavior in the OFT." (PMID 39179578, 2024).
metabolic syndrome (19 papers, 2009 to 2024). A cluster of metabolic risk factors for CARDIOVASCULAR DISEASES and TYPE 2 DIABETES MELLITUS. "In contrast, rs2292912 in the CRY2 gene and rs934945 in the PER2 gene were associated with dyslipidemia in the men (p = 0.02, and <0.001, respectively)." (PMID 34066863, 2021). "In humans, CLOCK gene SNPs are connected to body weight, metabolic syndrome risk, and insomnia, while PER2 and PER3 gene SNPs are linked to sleep disturbances." (PMID 32050674, 2020). "A notable proportion of genes within the enriched pathways in liver are related to the biological clock, including Wee1, Per2 and Slc5a6, each previously reported to be associated with the development of metabolic syndrome." (PMID 30619467, 2018). "In human subjects, PER2 has also been linked to metabolic syndrome." (PMID 34681805, 2021). "Moreover, a single-nucleotide polymorphism in PER2 has been linked to higher plasma cholesterol and triglycerides in subjects with metabolic syndrome." (PMID 34681805, 2021). "All this evidence suggests that PER2 disruption could lead to metabolic syndrome and altered plasma lipids, increasing CVD risk." (PMID 34681805, 2021). "Our findings link circadian gene variants to the risk factors of the metabolic syndrome, since Npas2 was associated with hypertension (P-value corrected for multiple testing = 0.0024) and Per2 was associated with high fasting blood glucose (P-value corrected for multiple testing = 0.049)." (PMID 19470168, 2009). "In addition, Per2 SNP rs934945 was associated with the metabolic syndrome." (PMID 19470168, 2009). "PER2 is a circadian rhythm gene that, when disrupted, can lead to cognitive decline, impaired learning, and metabolic syndrome." (PMID 37239811, 2023). "Post-BWRP changes in the methylation levels of clock, cry2 and per2 genes occurred in the entire population, together with hypermethylation of clock and per3 genes in males and in subjects with metabolic syndrome." (PMID 36497566, 2022). "Metabolic syndrome in humans is associated with the transcription of CRY1 and PER2 in adipose tissue." (PMID 32050674, 2020). "Human research has recognized polymorphisms and transcription motifs of circadian rhythm genes, such as CRY2, CLOCK, ARNTL, PER2, or NPAS2, which are linked with hypertension, metabolic syndrome, or T2DM." (PMID 32050674, 2020). "Other studies have shown associations between CRY1 and CRY2 polymorphisms and blood pressure in patients with metabolic syndrome, or associations between PER2 and BMAL1 polymorphisms and the non-dipper phenotype in 372 young hypertensive patients." (PMID 37298261, 2023). "Thus, metabolic syndrome, T2DM, and stroke are associated with CLOCK gene variants, while myocardial infarction is associated with CRY2 and PER2 gene variations." (PMID 32050674, 2020). "Changes in Per2, Bmal1 and Cry1 mRNA expression are related to human metabolic syndrome." (PMID 25799429, 2015). "A previous study demonstrated that continuous incubation of fibroblasts expressing PER2::LUC with nobiletin enhanced the circadian rhythm amplitude and protected against metabolic syndrome." (PMID 28152057, 2017). "Despite a small number of subjects, our results in the MS group suggest a link between PER2 and REV-ERB ALPHA genes with metabolic syndrome." (PMID 25365257, 2014). "In addition, Per2 (a transcriptional repressor of circadian rhythm) mutant mice do not show any metabolic syndromes, but show significant attenuation of CLDN5 expression and an increase in retinal permeability." (PMID 37095509, 2023).
myocardial ischemia (19 papers, 2013 to 2026). A disorder of cardiac function caused by insufficient blood flow to the muscle tissue of the heart. "Per2−/− mice have larger infarct sizes with deficient lactate production during myocardial ischemia, suggesting that PER2 protects the heart by regulating catabolism/energy." (PMID 34659637, 2021). "The reduction of glycogen storage leads to enlarged infarct areas in mice with PER2 mutation as a result of lowered glycolysis during myocardial ischemia." (PMID 32050674, 2020). "It has beenshown that the protein PER2 has a cardioprotective role during myocardial ischemia inmice, andmutation of the PER2 gene is associated with a shorter circadian periodduring constant darkness (Vukolic etal., 2010)." (PMID 29767668, 2018). "In contrast to Clock−/−, Per2−/− mice have larger infarct sizes with deficient lactate production during myocardial ischemia." (PMID 23977055, 2013). "In addition, it has been found that Per2 overexpression, due to light exposure, was associated with a reduction in the infarct size related to myocardial ischemia in mice." (PMID 34681805, 2021). "In fact, our recent studies found that intense light exposure of mice significantly increased cardiac Per2 levels which was associated with reduced troponin I levels and smaller infarct sizes in an in-situ model for myocardial ischemia when compared to room light conditions." (PMID 28448534, 2017). "Under myocardial ischemia, PER2 knockout mice have a dramatically increased infarct size due to impaired glycolysis and depletion of glycogen stores; thus, PER2 can regulate fatty acid metabolism in the ischemic myocardium." (PMID 40429770, 2025). "Upregulated miRNA-21 facilitates increased glycolysis via Per2-dependent mechanisms in myocardial ischemia." (PMID 40771283, 2025). "Recently, our group determined that the circadian rhythm protein Period 2 (PER2) provides robust cardio-protection from myocardial ischemia (MI) in an animal model." (PMID 36386382, 2022). "On the other hand, increasing circadian Per2 amplitude via intense light exposure facilitated cellular adaptation to myocardial ischemia and regulated endothelial barrier function during hypoxia." (PMID 33562664, 2021). "In fact, this is in line with recent studies that found endothelial expressed PER2 as the dominant player in protection from myocardial ischemia and reperfusion injury." (PMID 33382840, 2020). "On the other side, PER2 appears to play an important role during myocardial ischemia and reperfusion injury in general, as tissue-specific deletion of Per2 in myocytes, bone marrow cells, megakaryocytes or endothelial cells increase myocardial damage." (PMID 33382840, 2020). "As compromised platelet aggregation reduces myocardial IR-injury, these findings stand in contrast to recent findings on PER2 as an endogenous protective mechanism during myocardial ischemia." (PMID 33382840, 2020). "PER2 knockout mice had more extensive infarct sizes, and the PER2 in the heart exhibits an essential function during inflammation in myocardial ischemia and reperfusion." (PMID 32050674, 2020). "They demonstrated that PER2 is a downstream target of adenosine receptor A2b, which leads to stabilization of PER2 during myocardial ischemia and subsequent stabilization of hypoxia-inducible factor-1α and induction of glycolysis." (PMID 28825119, 2018). "Taken together, these data show that intense light mediated cardioprotection is abolished in miR-21-/-mice and suggest that miR-21 is a downstream target of light elicited Per2 in cardioprotection from myocardial ischemia and reperfusion injury." (PMID 28448534, 2017). "Studies on myocardial ischemia and reperfusion injury revealed larger infarct sizes and abolished light elicited Per2 cardioprotection in miR-21-/- mice." (PMID 28448534, 2017).
myocardial ischemia (continued). "After confirming that miR-21 was necessary for Per2 regulated pathways such as glycolysis, we next investigated the role of miR-21 in myocardial ischemia and reperfusion injury." (PMID 28448534, 2017). "Based on our findings that IPC increased cardiac miR-21 in a Per2 dependent manner, we next exposed wildtype controls or miR-21-/- mice to 3 h of intense light prior to myocardial ischemia and reperfusion injury as done previously in Per2-/- mice." (PMID 28448534, 2017). "Our recent studies found an important role of light elicited Per2 in controlling glycolysis during myocardial ischemia." (PMID 28448534, 2017). "After confirming a cardio-protective role of miR-21 in myocardial ischemia and reperfusion injury, we next investigated miR-21 as a potential downstream target of Per2 in myocardial ischemia and reperfusion injury." (PMID 28448534, 2017). "In summary, these studies reveal an important role of cardiac Per2 for fatty acid metabolism and inflammation during myocardial ischemia and reperfusion, respectively." (PMID 23977055, 2013). "This suggests that Per2 is particularly important in controlling transcription under pathologic conditions such as myocardial ischemia." (PMID 23977055, 2013). "Taken together, these data suggest a strong anti-inflammatory role of Per2 during myocardial ischemia and reperfusion." (PMID 23977055, 2013). "Taken together, these data confirm a dominant role of Per2 for lactate production during myocardial ischemia and suppose different roles for Per2 during ischemia or reperfusion." (PMID 23977055, 2013). "To gain insight into innate cardiac Per2 mediated adaptive mechanisms during myocardial ischemia we performed a detailed microarray analysis using different ischemia and reperfusion protocols." (PMID 23977055, 2013). "As lactate measurements in whole blood indicated an exclusive role of Per2 in controlling lactate production during myocardial ischemia, we next performed gene array studies using various ischemia-reperfusion protocols comparing wildtype and Per2−/− mice." (PMID 23977055, 2013). "Nuclear magnetic resonance studies further confirmed a regulatory role for Per2 in cardiac fatty acid metabolism during myocardial ischemia." (PMID 23977055, 2013). "Our group found impaired glycolysis during myocardial ischemia and severe depletion of glycogen storages leading to dramatically increased infarct sizes in Per2−/− mice." (PMID 23977055, 2013). "The question addressed in this study was to understand the contribution of Per2 to cardiac metabolism during myocardial ischemia and reperfusion." (PMID 23977055, 2013). "In contrast, we found recently an important role of Per2 for carbohydrate metabolism during myocardial ischemia." (PMID 23977055, 2013). "Because perioperative MI is the most common perioperative cardiovascular complication and sedative-hypnotics can alter the expression of PER2, a sedative-mediated downregulation of PER2 could be detrimental if myocardial ischemia and reperfusion occurs." (PMID 36386382, 2022). "Further, studies point to the protective effect of the Per2 gene in myocardial ischemia." (PMID 36557311, 2022). "Per2 has been shown to play a cardioprotective role in myocardial ischemia." (PMID 33668521, 2021). "Similarly, both Rev-erbα and Per2 agonists prevented severe injury of the heart in rodent models of cardiac ischemia reperfusion." (PMID 34488619, 2021). "In the mouse heart, PER2 has a protective function during myocardial ischemia." (PMID 32050674, 2020). "PER2 in the heart plays a crucial part in myocardial ischemia and fatty acid metabolism." (PMID 32050674, 2020). "Indeed, stabilization of Per2 has been suggested as a promising strategy for treating myocardial ischemia." (PMID 26098549, 2015). "Studies on cardiac lactate production during myocardial ischemia confirm a non-redundant role of Per1 and Per2 for cardiac metabolism, where lactate production is linked to Per2 but not Per1." (PMID 23977055, 2013).
myocardial ischemia (continued). "Moreover, co-immunoprecipitation studies confirmed a co-localization of both Per2 and Hif1α in the nucleus during myocardial ischemia." (PMID 23977055, 2013). "To test the hypothesis that cardiac Per2 represents an important regulator of cardiac metabolism during myocardial ischemia, we measured lactate during reperfusion in Per1−/−, Per2−/− or wildtype mice." (PMID 23977055, 2013). "Inflammation under the control of Per2 during myocardial ischemia and reperfusion." (PMID 23977055, 2013). "After uncovering an unexpected role of Per2 in controlling inflammation during myocardial ischemia and reperfusion, we next performed a pattern recognition analysis (heat map of biological functions) of differentially regulated genes in Per2−/− and wildtype mice." (PMID 23977055, 2013). "After confirming a dominant role for Per2 in regulating lactate metabolism during myocardial ischemia or reperfusion, we next pursued studies on Per2 dependent gene expression during myocardial ischemia or reperfusion to understand its impact on cardiac metabolism." (PMID 23977055, 2013). "In summary, performing a high throughput gene array screen in hearts from Per2−/− in conjunction with analysis of metabolism and inflammation unveil a novel role for Per2 in fatty acid beta-oxidation and inflammation during myocardial ischemia and reperfusion, respectively." (PMID 23977055, 2013). "In addition, Per2 gene ablation worsens the inflammatory response to myocardial ischemia." (PMID 39202335, 2024). "Finally, studies during reperfusion after 60 minutes of myocardial ischemia found a strong, so far unknown, anti-inflammatory role for cardiac Per2." (PMID 23977055, 2013). "Another study has shown that mice with Per2-/- had enhanced tissue damage from myocardial ischemia and lacked the capacity to enhance oxygen-efficient glycolysis." (PMID 34659637, 2021). "Studies in Per2-/- mice showed a lack of lactate production during myocardial ischemia and the inability to induce glycolytic pathways, a necessary adaptive mechanism during cardiac ischemia." (PMID 28448534, 2017).